CSMD1 (CUB and Sushi multiple domains 1)
Diseases named in the same sentence as CSMD1 in open-access papers (continued):
Sharing a sentence is not in itself a finding about the gene and the disease.
gastric cancer (13 papers, 2014 to 2025). A primary or metastatic malignant neoplasm involving the stomach. "Similar observations have been reported for CSMD1 in human gastric cancer, which was also mutated in multiple samples in the present study (11% of cases, 1/8 POSV595E and 3/28 UDV595E samples)." (PMID 37079639, 2023). "One possible explanation for this result is that functional site mutations in CSMD1-mut patients have a positive effect on the prognosis of patients with gastric cancer." (PMID 34828321, 2021). "In gastric cancer cells, CSMD1 downregulation has been associated with increased NF‐κB signalling, upregulation of c‐Myc and CCND1, and downregulation of E‐cadherin." (PMID 33506581, 2021). "In summary, CSMD1-mut in gastric cancer was associated with increased TMB and favorable survival." (PMID 34828321, 2021). "The loss of these chromosomes was reduced in CSMD1-mut patients, and we speculate that these changes may help to resist or delay the progression of gastric cancer." (PMID 34828321, 2021). "In summary, CSMD1-mut in gastric cancer was associated with increased TMB and favorable survival and may have potential significance in predicting the efficacy of anti-PD-L1." (PMID 34828321, 2021). "Recent studies in certain cancer types, e.g., gastric cancer, oesophageal cancer, and head and neck squamous cell carcinomas, have indicated the involvement of CSMD1 in response to immunotherapy." (PMID 36553598, 2022). "Second, these results are only based on the cohort follow-up survey from a public database, and the effect of CSMD1-mut on the growth and metastasis of gastric cancer needs to be verified by experiments in vivo and in vitro." (PMID 34828321, 2021). "For instance, miRNA-10b that targets the CSMD1 acted as an oncogenic factor in human gastric cancer through nuclear factor-κB (NF-κB) pathway." (PMID 34384362, 2021). "Finally, whether CSMD1-mut can be used as a predictive biomarker for the efficacy of anti-PD-L1 in patients with gastric cancer and even other tumors remains to be further verified and practiced." (PMID 34828321, 2021). "However, so far, there is no research to explain the general situation of CSMD1-mut in gastric cancer and the alterations in biological function caused by it." (PMID 34828321, 2021). "It has shown that CSMD1 is dramatically downregulated in gastric cancer (GC) tissues compared to normal tissues via RT-PCR, and the overexpression of microRNA-10b, a direct target of CSMD1 in GC cells, was found to increase GC cell vitality, migration, and invasion." (PMID 36553598, 2022). "Furthering the connection between Csmd1 and EMT showed a connection between Csmd1 and Nf-κß, a well-known EMT factor, where Csmd1 inhibition leads to increased Nf-κß activity and increased EMT phenotype in gastric cancer." (PMID 33530646, 2021). "The role of CSMD1 in gastric cancer has not been studied until the past two years." (PMID 34828321, 2021).
hepatocellular carcinoma (13 papers, 2016 to 2026). A malignant tumor that arises from hepatocytes. "These genes include the telomerase reverse transcriptase gene, TERT, CSMD1, a putative tumor suppressor that is frequently mutated in human hepatocellular carcinoma associated with HBV infection, FRAS1 and the mitochondrial encoded gene ND5." (PMID 35557512, 2022). "METTL16, through m6A methylation, reduces the RNA stability of lnc-CSMD1-7, which promotes the metastasis and progression of hepatocellular carcinoma." (PMID 41459114, 2026). "TERT, CSMD1, FRAS1 and ND5 are mutated in 28.6%, 5.7%, 5.2% and 5.3% of human hepatocellular carcinomas." (PMID 35557512, 2022). "In hepatocellular carcinoma, miR-10b was also demonstrated to promote cell viability and invasion through targeting CSMD1." (PMID 34384362, 2021). "It has been reported that CSMD1 is regulated by microRNA-10b in human hepatocellular carcinoma cells." (PMID 31592231, 2019). "In hepatocellular carcinoma, the HIF-1α/METTL16/lnc-CSMD1-7/RBFOX2 signaling axis has been shown to regulate interactions between tumor cells and the tumor microenvironment, particularly influencing cell behaviors such as epithelial–mesenchymal transition." (PMID 41459114, 2026).
autism (12 papers, 2014 to 2024). Persistent deficits in social interaction and communication and interaction as well as a markedly restricted repertoire of activity and interest as well as repetitive patterns of behavior. "These included the regions harboring known autism risk genes, CSMD1, NRXN2, and RBFOX1, all of which were found to be hypomethylated in both discovery and validation analyses." (PMID 36035158, 2022). "A previous exome sequencing study revealed that alterations in CSMD1 were associated with autism, which indicates the involvement of this gene in other psychological disorders." (PMID 33384710, 2020). "Moreover, a partial duplication of CSMD1 was associated with myoclonic seizures, developmental delay and autism in a child, and isolated CSMD1 deletions contributed to the epilepsy phenotype." (PMID 32315120, 2020). "Furthermore, rare variants in the CSMD1 gene have been reported to be involved in autism." (PMID 33384710, 2020). "Additional alterations were found in previously reported autism candidate genes, including three genes with alterations in multiple families (CEP290, CSMD1, FAT1, and STXBP5)." (PMID 24410847, 2014). "A total of 44 sporadic variants, including missense, silent, nonsense, and splice alterations, have been reported in CSMD1 (CUB and Sushi multiple domains 1, MIM# 608397) in individuals with developmental disorders and autism, suggesting that CSMD1 is likely an autism disorder gene." (PMID 39519104, 2024). "Interestingly, the contribution of the CSMD1 and MCPH1 genes to the formation of autism was also noted when these genes were involved in the duplication region." (PMID 35327368, 2022).
depression (12 papers, 2013 to 2024). "This gene has previously been associated with depression in a genome-wide association study (GWAS), and animal studies with CSMD1 knock-out mice also supported its role in the development of anxiety- and depression-related symptoms." (PMID 39457114, 2024). "Of thirteen depression‐associated DRPs, seven proteins including DDC, FGFR2, KIBRA, MED22, OLIG1, RAI1, SLIT2 were upregulated, whereas six proteins including COX3, CRHBP, CSMD1, FSTL1, GRIK4, and LMTK3 were downregulated." (PMID 39373701, 2024). "In summary, disruption of Csmd1 induces behaviors reminiscent of blunted emotional responses, anxiety and depression." (PMID 24244513, 2013). "Furthermore, anxiety- and depression-like behaviors, i.e. phenotypes we identified in Csmd1 KO mice, may mask the effects of the Csmd1 KO in complex context-dependent tests like e.g. social learning." (PMID 24244513, 2013).
head and neck squamous cell carcinoma (12 papers, 2005 to 2025). A squamous cell carcinoma that arises from any of the following anatomic sites: lip and oral cavity, nasal cavity, paranasal sinuses, pharynx, larynx, and salivary glands. "CSMD1 has mainly been associated with head and neck squamous cell carcinoma, but CSMD1 losses is also reported to contribute to the tumourigenesis of several other epithelial cancers, including BC." (PMID 23967248, 2013). "Deletion of 8p23.2 or reduced expression of CSMD1 has been associated with poor prognosis in head and neck squamous cell carcinomas and in prostate cancers." (PMID 16153303, 2005). "Preliminary evidence suggested that CSMD1 expression is lost in head and neck squamous cell carcinomas but that point mutations were rare [, and Schmidt, Richter and Scholnick, unpublished]." (PMID 16153303, 2005). "Also, studies have shown that deletion of CSMD1 is associated with poor prognosis in head and neck squamous cell carcinoma and prostate cancer." (PMID 27756250, 2016). "Although the region containing CSMD1 is frequently deleted in head and neck squamous cell carcinomas and prostatic adenocarcinomas, point mutations in the gene are relatively rare in primary squamous cancers and in squamous cell carcinoma cell lines (Schmidt, Richter and Scholnick, unpublished)." (PMID 16153303, 2005). "Taken together these data demonstrate that mechanisms other than point mutation are responsible for the aberrant CSMD1 expression in head and neck squamous cell carcinoma cell lines, and these data suggest potential targets for further investigation in primary tumors." (PMID 16153303, 2005). "In an effort to identify alternative mechanisms of inactivation, we have characterized CSMD1 expression and epigenetic modifications in head and neck squamous cell carcinoma cell lines." (PMID 16153303, 2005). "While CSMD1 transcripts are detectable in upper aerodigestive tract epithelium, preliminary analysis of several head and neck squamous cell carcinoma cell lines suggested that CSMD1 expression was lost in these lines." (PMID 16153303, 2005). "Our data clearly demonstrate that expression of normal CSMD1 transcripts is rare in head and neck squamous cell carcinoma cell lines." (PMID 16153303, 2005). "Taken together, our data suggest that CSMD1 function is lost in head and neck squamous cell carcinoma cell lines through a variety of mechanisms other than point mutagenesis." (PMID 16153303, 2005). "CUB and sushi multiple domains 1 gene (CSMD1), the first gene cloned from this family, was described as a postulated adhesion molecule or transmembrane protein with a role as tumor suppressor in head and neck squamous cell carcinoma." (PMID 39235515, 2025). "A recent study in head and neck squamous cell carcinomas highlighted that genomic aberrations including EGFR amplifications, AKT1 amplifications and CSMD1 deletions, but not PIK3CA, were highly associated with responsiveness to PI3K-targeted drugs." (PMID 34404439, 2021).
melanoma (12 papers, 2014 to 2025). A malignant, usually aggressive tumor composed of atypical, neoplastic melanocytes. "Furthermore, CSMD1 mutations occurred in three of the seven cases, which in melanoma produce neoantigens mimicking bacteria (Burkholderia pseudomallei), a positive predictor for anti-CTL4 therapy." (PMID 36980598, 2023). "No other exonic variants were detected that have previously been implicated in melanoma, although high-level mutations were detected in tumour suppressor genes (TRPS1 and CSMD1), pinpointing to their role as potential disease drivers in this patient." (PMID 29075515, 2017). "They include the prostate cancer suppressor NXK3-1, the gene CSMD1, which is recurrently deleted in melanoma, and the phosphatase DUSP4, which is involved in negative feedback control of EGFR signaling in lung adenocarcinoma." (PMID 25160065, 2014). "In melanoma cells, an increased expression of CSMD1 reduces the rate of cell migration." (PMID 36553598, 2022). "CSMD1 was recently shown to interact with SMAD3 in melanoma cells." (PMID 32701512, 2020). "CSMD (CUB and Sushi Multiple Domains 1) can interact with Smad3, confirming the role of CSDM1 as a tumor suppressor gene in melanoma cells." (PMID 39969704, 2025).
Anxiety (7 papers, 2013 to 2024). Intense feelings of nervousness, tension, or panic often arise in response to interpersonal stresses. "Studies on CSMD1 knockout mice suggest that the depletion of CSMD1 expression is linked with abnormal emotion/affect behavior, hyperactivity and increased anxiety-related response." (PMID 35162247, 2022). "Specifically, over-expression of C4/C4A components might contribute to the enhancement of anxiety-like behaviors, social impairment and working memory deficits, whereas depletion of the CSMD1 genetic locus induces emotional and cognitive defects." (PMID 35532796, 2022).
colorectal cancer (7 papers, 2013 to 2025). A primary or metastatic malignant neoplasm that affects the colon or rectum. "The allelic loss, copy number aberrations, mutations, and methylations of CSMD1 have been detected in various malignant tumours such as head and neck tumor, colorectal cancers, liver cancer, and so on 5-16." (PMID 31592231, 2019). "For example, only 5 out of 72 cases of pediatric neuroblastoma harbor mutations of ARID1B and only 5 out of 26 cases of colorectal cancers harbor mutations of CSMD1." (PMID 30627328, 2018). "Our goal was to characterize the relationships between CSMD1 somatic mutations, allele imbalance, DNA methylation, and the clinical characteristics in colorectal cancer patients." (PMID 23505554, 2013). "By examining multiple methods of CSMD1 alterations (mutation, methylation, and allele loss), we observed significant correlations of CSMD1 loss of function with early age of diagnosis in colorectal cancer patients." (PMID 23505554, 2013). "In this follow-up study, we used next generation sequencing to further confirm the important role of CSMD1 mutations in colorectal cancer progression." (PMID 23505554, 2013). "The correlation between CSMD1 loss of function and clinical presentation may help provide insight into the neoplastic development of colorectal cancer." (PMID 23505554, 2013). "We previously reported frequent mutations of CSMD1 in colorectal cancers." (PMID 23505554, 2013). "In conclusion, our study indicates that CSMD1 is highly mutated in colorectal cancer with a C:G bias, suggesting that methylation may contribute to the gene-specific hypermutator phenotype." (PMID 23505554, 2013). "Therefore, based on our results and the validation of future studies, CSMD1 methylation may be identified as an instrumental mechanism in driving somatic mutations in CSMD1, indicating itself as an underlying agent in early colorectal cancer development." (PMID 23505554, 2013). "Reduced expression of CSMD1-3 proteins was reported in colorectal carcinoma compared to patient-matched normal tissue." (PMID 39235515, 2025). "Based on a Kaplan-Meier Survival Analysis, TCGA sequencing data revealed that colorectal cancer patients with CSMD1 alterations have a significantly lower probability of survival than patients without CSMD1 alterations (log-rank test p = .000565)." (PMID 23505554, 2013). "With such evidence, the identification of CSMD1 alterations has the potential to be used as markers in colorectal cancer prognosis." (PMID 23505554, 2013). "Although NEUROG1 and CDKN2A have shown to be methylated in colorectal cancers, CSMD1-3 methylation did not correlate with NEUROG1 (p = 0.432, R = .1081) or CDKN2A (p = 0.537, R = .08488) methylation, though these two markers did positively correlate with each other (p<0.01)." (PMID 23505554, 2013).
epilepsy (7 papers, 2018 to 2025). A brain disorder characterized by episodes of abnormally increased neuronal discharge resulting in transient episodes of sensory or motor neurological dysfunction, or psychic dysfunction. "This study suggests that CSMD1 is associated with epilepsy and is a novel causative gene of DEE and generalized epilepsies." (PMID 40330149, 2024). "To date, there is insufficient evidence to explain the direct relationship between duplication of CSMD1 and epilepsy." (PMID 32477112, 2020). "However, we suggest that the overexpression of CSMD1 due to 8p23.2 duplication leads to abnormal synaptic connectivity and it may contribute to the occurrence of epilepsy." (PMID 32477112, 2020). "The overall results favor the view that CSMD1, STIM2, and RGS7BP genes could contribute to epilepsy and migraine phenotypes in our family." (PMID 32315120, 2020). "Thus, considering the oligogenic origin of epilepsies, it is reasonable to speculate that the detrimental effect of the rearrangement on CSMD1 and hypothetically STIM2, together with RGS7BP deletion may contribute to the epilepsy/migraine phenotypes in our family." (PMID 32315120, 2020).
Hypertension (7 papers, 2011 to 2023). The presence of chronic increased pressure in the systemic arterial system. "GAS1 is a cell cycle inhibiting protein that has been linked to cancer and CSMD1 has been associated with hypertension and peripheral artery disease in GWAS of persons of Asian descent." (PMID 21901158, 2011). "Interestingly, other intronic SNPs in the CSMD1 loci have been reported to be associated with hypertension or blood pressure response to hydrochlorothiazide, an antihypertensive drug." (PMID 37936055, 2023). "Moreover, the CSMD1 gene was associated with an increased risk of hypertension among Korean patients." (PMID 33316892, 2020). "It was also reported that CSMD1 was associated with multivariate phenotype defined as low levels of low density lipoprotein cholesterol (LDL-C < or = 100 mg/dl) and high levels of triglycerides (TG > or = 180 mg/dl), associated with hypertension." (PMID 27104857, 2016). "Many reports showed that CETP, LIPC and LIPG were associated with HDL and LDL and that MTHRR had known main effects for LDL and blood pressure, NR1I3 for lipid metabolism, PLTP for LDL, FOXO1 for LDL and hypertension, SMAD9 for hypertension, and CSMD1 for SBP." (PMID 27104857, 2016).
Parkinson disease (7 papers, 2021 to 2025). A progressive degenerative disorder of the central nervous system characterized by loss of dopamine producing neurons in the substantia nigra and the presence of Lewy bodies in the substantia nigra and locus coeruleus. "This study aimed to investigate the relationship between CSMD1 gene and susceptibility to Parkinson's disease in population of northern China." (PMID 33628416, 2021). "Another variant in CSMD1, rs12681349, was identified as a novel Parkinson's disease locus by stratified GWAS, which was analyzed in relation to Parkinson's disease in Iranian population, but no positive results were found." (PMID 33628416, 2021). "Furthermore, recent GWAS and SNP analysis have shown that CSMD1 is closely related to neurological diseases such as SZ and Parkinson’s disease (PD)." (PMID 36553598, 2022). "Multicenter, large sample, and multiethnic studies may better explore the mechanism of CSMD1 gene on Parkinson's disease." (PMID 33628416, 2021).
autism spectrum disorder (6 papers, 2016 to 2024). A spectrum of developmental disorders that includes autism, and Asperger syndrome. "Moreover, emerging CSMD1 variants have been identified as the molecular basis of autism spectrum disorder (ASD) and a NDD with cerebellar hypoplasia." (PMID 38816421, 2024). "CSMD1 protein coding gene has been previously associated with autism spectrum disorders (ASD)." (PMID 35836289, 2022). "In addition to CSMD1, heterozygous de novo and inherited missense CSMD3 variants were recently described as the genetic basis for a NDD characterized by ID and autism spectrum disorder." (PMID 38816421, 2024). "CSMD1 is an important regulator of complement activation and inflammation, while RBFOX1 encodes for an mRNA-splicing factor linked to autism spectrum disorders." (PMID 34868193, 2021).
neuroblastoma (6 papers, 2013 to 2018). Neuroblastoma (NB) is the most common solid, extracranial childhood tumor. "Structural defects caused by chromothripsis have been found to recurrently affect ATRX, ODZ3 (odd oz/ten-M homolog 3 (Drosophila)), PTPRD (protein tyrosine phosphatase, receptor type D), and CSMD1 (CUB and sushi multiple domains 1) in high-risk neuroblastoma." (PMID 28035989, 2016). "Since recurrent structural variants and a missense mutation of CSMD1 gene have been found in neuroblastoma, this gene may be the promising gene target for 8p LOH in neuroblastoma." (PMID 29296183, 2017).
cannabis dependence (5 papers, 2012 to 2021). Physical and psychological dependence on the drug cannabis. "Moreover, in a recent large GWAS study of cannabis dependence, a CSMD1 marker was found to be associated with cannabis dependence at a genome-wide level of significance." (PMID 29675039, 2018). "Furthermore, four other genes, FAM38B (cocaine dependence in black women), PTPRM (marijuana dependence in black women), CSMD1 (nicotine dependence in black women), and RELN (cocaine dependence in white men), contain at least one SNP that met the SNP-based relaxed threshold of significance." (PMID 23365539, 2012).